IGF1 (insulin like growth factor 1)
Diseases named in the same sentence as IGF1 in open-access papers (continued):
Sharing a sentence is not in itself a finding about the gene and the disease.
tumor (continued). "Potential predictive factors evaluated were: sex, age, and body mass index at baseline; and GH, insulin-like growth factor-1 (IGF-1), and tumor volume (TV) at baseline and week 12, using univariate regression analyses." (PMID 31879842, 2020). "Predictors of failure to respond to surgery after complete initial visible tumor resection are higher IGF-1 level at diagnosis (P = 0.024) and CS invasion (P = 0.028)." (PMID 32843993, 2020). "In contrast to these studies, IGFBP2 behaves as tumor suppressor in our experiments: it inhibits the IGF1-induced proliferation and the pro-survival PI3K/Akt pathway in 4T1 cells." (PMID 32133294, 2020). "Our results indicate that the tumor-growth promoting function of ASCs is influenced by the balance of IGF1/IGFBP2." (PMID 32133294, 2020). "The tumor volume was significantly higher in the xenografts containing ER positive MCF-7 cells with IGF-1 overexpression compared to the control in the mouse model; IGF-1 potentiated the invasive ability of MCF-7 cells." (PMID 32435229, 2020). "At 24 days after injection, CR-fed mice exhibited lower tumor volume concomitant with reduced body weight, body fat, serum IGF-1, leptin, and insulin." (PMID 31906264, 2020). "Consistent with this research, we also observed that miR-4500 was lowly expressed in BC, and miR-4500 exerted anti-tumor roles via targeting IGF1." (PMID 33298061, 2020). "We know that the high expression of IGF1 and inflammatory factors can promote tumor development by changing the tumor microenvironment." (PMID 32133283, 2020). "We further observe a regulatory role of the molecule in pathways associated with PDAC ECM remodeling and tumor-stromal crosstalk, such as INS/IGF-1, RAS/MAPK, laminin interactions and collagen biosynthesis." (PMID 32660466, 2020). "The goal of therapeutic strategies for this condition is to normalize GH and IGF-1 levels, remove tumor mass and/or stabilize tumor growth while maintaining normal pituitary function." (PMID 33680922, 2020). "Our results show that ASCs with altered genetic background promote tumor progression by unbalanced IGF1 and IGFBP2 secretion, which leads to enhanced growth of breast epithelial cells and favors tumorigenesis." (PMID 32133294, 2020). "In summary, this study describes the action of IGF-1 on tumor proliferation, migration, invasion and the maintenance of stemness in SCC-4, which shows high IGF-1 receptor expression but does not synthesize this growth factor." (PMID 32899449, 2020). "Further subgroup analysis revealed an interaction between IGF-1 and BMI (P for interaction = 0.009) or tumor size (P for interaction = 0.044) in predicting RFS." (PMID 32391265, 2020). "To further investigate the concentrations of MMP-9 and IGF-1 within the tumor microenvironment, we also analyzed the tumor tissue 17 days after Plasmodium infection." (PMID 32972437, 2020). "Expression of IGF-1 has also been found in tumor-associated macrophages in CRC and other solid cancers, and its function associated with tumor cell proliferation, migration, and angiogenesis." (PMID 32425932, 2020). "Fibroblasts, the most abundant cell type found in tumor stroma, secrete several growth factors, including IGF-1, and cytokines, chemokines and metalloproteinases." (PMID 32899449, 2020). "Diet modification is known to alter the IGF-1/Akt pathway and affect the expression of microRNA involved in tumor initiation, growth and metastases." (PMID 32211051, 2020). "Numerous studies concerning the members of the IGF system in different tumor developments (including CRC) were mostly focused on IGF1, IGF1R, and IGFBP1-3." (PMID 31623387, 2019). "IGF1-IONPs exhibited excellent tumor penetration ability after IV administration in an orthotopic patient-derived tumor model." (PMID 31824928, 2019). "The severity of clinical manifestations depends on the levels of GH and IGF-1, tumor size, and time to diagnosis." (PMID 30269264, 2019).
tumor (continued). "Most studies indicate that KL functions as a tumor suppressor and modulates several signaling pathways such as insulin-like growth factor-1 (IGF-1), FGF, and Wnt/β-Catenin." (PMID 31681612, 2019). "An immunofluorescence double staining assay further confirmed that IGF-1 expression in the tumour stroma was closely correlated with the density of CAFs." (PMID 31076571, 2019). "In 4-months IGF1 normalized again, the metastatic lesion in left lung reduced, and a 24-month follow-up showed further reduction in the secondary tumor and a stabilized metastases." (PMID 32382711, 2019). "The nobiletin- and IGF1-treated group exhibited significantly higher tumor viability than the group treated with nobiletin alone." (PMID 31354472, 2019). "Research supports the role of insulin and IGF-1 as important growth factors, acting through the tyrosine kinase growth factor cascade in enhancing abnormal tumor growth." (PMID 31719636, 2019). "IGFBP2 is the second most abundant IGF-binding protein (after IGFBP3), functions as a carrier for IGF-1 and likely promotes tumor progression through IGF-1R pathway." (PMID 31399589, 2019). "Several studies have reported that GH is a potent inducer of EMT in tumor and normal cells, directly as well as via secondary effectors like IGF1 and TGFβ." (PMID 32382711, 2019). "Somasundaram and colleagues demonstrated that tumor-associated B cells induce resistance to these inhibitors in vitro through the secretion of IGF-1 and confirmed an increase of CD20 and IGF-1 gene expression in tumor of resistant patients." (PMID 31086070, 2019). "NICTH is commonly associated with excessive secretion of immature insulin-like growth factor (IGF)-2 precursor or IGF-1, by mesenchymal or epithelial tumor cells." (PMID 29166433, 2019). "This complicates therapeutic management, because it is considered important to keep IGF1 concentration below +2 SDS, because of the increased risk of cardiovascular diseases and neoplasm." (PMID 30759961, 2019). "In contrast, the expression of GGI-GS, DiLeoRBloss-GS, Rbloss-GS, CIN70-GS, E2FmotifCellCycleAssociated-GS, Gene70-GS, E2F4activation-GS, AURKA-GS, PTEN-GS, E2Factivation-GS, and IGF1-GS were significantly higher in the noCCCA tumours (all p < 0.0001)." (PMID 31892336, 2019). "Here we provide additional pieces by reporting on changes in lifespan and tumor incidence that accompany IGF1 expression driven by keratin-14 promoter in FVB/N-derived transgenic K14/mIGF1 female mice." (PMID 30981207, 2019). "It was reported that abnormal activation of IGF-1 promoted tumor cell growth and metastasis, but the exact mechanism beneath IGF-1 activation in HCC remains vague." (PMID 31885628, 2019). "Insulin-like growth factor-1 (IGF-1) is a hormone with anti-apoptotic and mitogenic potentials correlated to the tumor growth and progression toward malignancy." (PMID 31752829, 2019). "Although studies have shown that decreased levels of IGF-1 are associated with HCC development, there are lines of evidence showing tumor-promoting effects of IGF-1." (PMID 30700007, 2019). "Studies in tumor-bearing mice show that fasting for 72 h reduces plasma glucose concentrations by ~40% and IGF-1 by ~70%." (PMID 31293576, 2019). "Elevated levels of STAT3-activating ligands, such as IGF-1, TGFα, or IL-6, have also been detected in the serum and/or the tumor microenvironment of patients with various malignancies." (PMID 31399589, 2019). "Although these treatments stabilized tumor growth over 4 years, IGF-1 was normalized only after pegvisomant treatment, although access to this medication was intermittent." (PMID 31125088, 2019). "Despite the positive gains that we and others have observed with IGF-1, this cytokine has been reported to participate in tumor formation." (PMID 31113444, 2019).
tumor (continued). "In normal tissue, ‘germ cell–Sertoli cell junction signaling’, ‘ERK/MAPK signaling’, and ‘HIPPO signaling’ were the top hits, while in tumor tissue, ‘IGF‐1 signaling’, ‘ephrin A signaling’, and ‘androgen signaling’ were among the top hits." (PMID 31520575, 2019). "In most patients, preoperative SSAs are proven to reduce GH and IGF-1 levels, stimulate tumor shrinkage, and soften tumor consistency." (PMID 31575930, 2019). "In an experimental study, mice fed a low-protein diet showed 45% smaller tumor size and 30% less serum concentration of IGF-1 than high protein consumers." (PMID 31333806, 2019). "In vivo studies demonstrated that CAFs can mediate autophagy and irradiated tumor cell recovery through insulin-like growth factor 1-mediated mechanisms." (PMID 30828330, 2019). "Functional analyses of miR-28-5p revealed tumor suppressive properties caused by the inhibition of Rap1b, E2F6, IGF-1, IL-34, and AKT." (PMID 31921670, 2019). "In fact, in PDAC cells, Kras-mutated Sonic Hedgehog activation increases the expression of IGF-R1 on tumor cells and the secretion of IGF1 by stellate pancreatic cells." (PMID 30366466, 2018). "More importantly, we demonstrated that IGF1-cultured DLD-1 cells exhibited an enhanced tumor-initiating ability in vivo as compared to their naïve counterparts." (PMID 30257507, 2018). "Evidence shows that IGF1 promotes tumor cell differentiation and growth through autocrine or paracrine means." (PMID 29651441, 2018). "Of the 70 MP subtype tumor samples from TCGA, 11 showed amplification of the IGF1 gene, and expression of IGF1 in these tumors was significantly higher than in normal tissue and in EP subtype tumors." (PMID 29725014, 2018). "Skeletal muscle wasting involves the production of pro-inflammatory cytokines derived from tumor and immune cells, and negative regulation of insulin-like growth factor-1 signaling by myostatin and activin." (PMID 29630652, 2018). "KLa has tumor-suppressing roles on cell proliferation and survival, resulting from inhibition of the IGF-1/insulin signaling pathway and EMT." (PMID 29731962, 2018). "Our results suggest that PON2 overexpression reduces the tumor forming potential of ID8 cells by reducing the IGF-1 signaling and its signaling pathway." (PMID 29531225, 2018). "Most interestingly, expression of IGF1 was significantly upregulated in MP subtype tumors with significance remaining the same even after adjustment of expression data for non-tumor cell effect." (PMID 29725014, 2018). "IGF-1 gene expression in tumor tissues and plasma IGF-1 level were significantly reduced in mice that received ID8hPON2 cells when compared to mice that received ID8EV cells." (PMID 29531225, 2018). "In confirmation of this, overexpression of IGFBP-4 in a malignant prostate epithelial cell line decreased the proliferative response to IGF1 and delayed tumor development when transfected cells were transplanted into nude mice." (PMID 29503631, 2018). "Similar to our findings showing that BC cells increase the secretion of IGF-1 in CAFs, the tumor-conditioned media of TNBC cell lines – including MDA-MB-231 cells – stimulates the expression IGF-1 in human mesenchymal stem cells." (PMID 29535813, 2018). "Remarkably, the migration capacity of tumor-derived PaSCs is also prominently greater both at basal conditions and after IGF-1 stimulation." (PMID 29475434, 2018). "This study highlights the therapeutic potential of dBP4 as an approach to block the tumour-promoting actions of IGF1." (PMID 30348128, 2018). "Our results show that ASCs with altered genetic background promote tumor progression by upregulating the expression of genes, such as IGF1, which favors carcinogenesis." (PMID 30185144, 2018). "Of interest, there was a significant correlation between vascular invasion by the tumor and amount of IGF-1." (PMID 30064393, 2018). "The data highlight the therapeutic potential of dBP4 as an approach to blocking the tumour-promoting actions of IGF1." (PMID 30348128, 2018).
tumor (continued). "High IGF1 levels and both lower and higher levels of IGFBP3 are predictor risk factors for secondary tumour development in patients with HNSCC." (PMID 30594912, 2018). "We found that elevated production of insulin-like growth factor 1 by polyploid ASCs rendered them more potent in tumor growth promotion in vitro." (PMID 30185144, 2018). "A recent review has highlighted differences between locally and systemically delivered IGF1 in other disease models so our future studies will include comparisons between intra-tumour (local) and systemic delivery." (PMID 30348128, 2018). "Future studies evaluating the role of the IGF1 signaling pathway in tumor infiltrating immune cells in gynecologic malignancies will deepen our understanding of the feasibility of the combined therapy." (PMID 29922232, 2018). "Administration of IGF1R-selective inhibitors (A12) reduced IGF1-induced effects and was associated with a significant reduction of HCC tumor growth." (PMID 29702590, 2018). "Simple DR reduced both serum IGF‐1 and tumor prevalence at necropsy in dead mice, and these effects were not altered by the replenishment of the diet with either NEAA or EAA." (PMID 29943496, 2018). "This is consistent with the ability of IGF‐1 to mediate chemotaxis of several cell types including tumor cells and to induce macrophage migration in transwell chambers." (PMID 29907597, 2018). "Inactivation of ΔNp63 expression indeed reduces tumour cell responsiveness to IGF1 stimulation, and inhibits the growth potential of HNSCC cells." (PMID 30594912, 2018). "In this study, serum IGF‐1 levels and tumor prevalence were significantly higher only in the ad libitum‐fed aged mice." (PMID 29943496, 2018). "It is interesting that survival time in HCC patients treated with resection of the tumor is closely related with IGF1 expression in the liver tissue adjacent to tumor." (PMID 29702590, 2018). "Recombinant IGF-1 increased tumor cell expression of FGFR-3 as did co-cultured TAB cells, and reciprocally, recombinant FGF-2 induced IGF-1 production in NB cells as did co-cultured tumor cells." (PMID 28928360, 2017). "After 14 days, (tumor-conditioned) NB cells showed high transcript levels for IGF-1, IL-1 (α/β) and PDGF-Α/-Β whereas non-co-cultured (unconditioned) NB cells expressed low levels or none at all." (PMID 28928360, 2017). "PRAS40 is phosphorylated in response to insulin or IGF-1 treatment, and plays an important role in the tumor cell proliferation induced by these growth factors." (PMID 28978182, 2017). "On the other hand, E0771 cells responded to IGF-1 stimulation and expressed much higher level of IGF-1R than B16F1 cells, suggesting that HSC-Ad rely more on the IGF-1/IGF-1R signaling pathway to regulate E0771 tumor growth." (PMID 28989976, 2017). "α-Klotho acts as a tumor suppressor by inhibiting insulin/IGF-1 signaling in breast cancer, lung cancer, pancreatic cancer, gastric cancer, liver cancer, colon cancer, and ovarian cancer." (PMID 29250031, 2017). "Both insulin and IGF1 are promoters of cell proliferation and inhibition of apoptosis in tumor cells." (PMID 28954281, 2017). "We found that MG tumor latency time in X10 and IGF1 (compounds with a high affinity towards the IGF1R) treatment groups was significantly decreased." (PMID 28173837, 2017). "We found high (moderate to strong) cytoplasmic expression of MET and IGF-1 in 82.8% and 6.1% of valid tumor samples, respectively." (PMID 28742836, 2017). "Chronic treatment with compounds that possess a high affinity towards the IGF1R, IGF1 and the insulin analogue X10, significantly decreased the tumor latency time." (PMID 28173837, 2017).
tumor (continued). "The overall efficacy of SSA is ~35% in biochemical remission rate (mean GH levels < 2.5 μg/L and IGF-1 normalization) and ~70% in oncological response rate (tumor volume shrinkage > 20%)." (PMID 28396686, 2017). "The growth stimulating effects of estrogens are mediated through ERβ and insulin-like growth factor 1 signaling to inhibit caspase 3 activity and reduce tumor cell apoptosis." (PMID 28877739, 2017). "Tumor mice receiving a chronic X10 and IGF1 treatment showed increased expression of glycolysis related genes and are associated with a decreased tumor latency time." (PMID 28173837, 2017). "Quantitative evaluation of IGF-1/IGF-1R expression combined with molecular assessment of T2E status or ERG protein expression represents a useful marker for tumor progression in localized PCa." (PMID 28545426, 2017). "The stimulation of MDA-MB-435 + E-cad cells with insulin or IGF1 decreased the bisecting N-glycans expression on E-cadherin which consequently up-regulated mesenchymal markers with the enhancement of tumour cell invasion." (PMID 28880250, 2017). "Rather, estrogens were found to activate ERβ and increase insulin-like growth factor 1 (IGF1) signaling pathways that act to reduce tumor cell apoptosis." (PMID 28877739, 2017). "Usually, insulin promotes proliferation of tumour cells only at higher concentrations than IGF1, possibly since it predominantly acts via type 1 IGFRs." (PMID 28316059, 2017). "In the current study, we investigated the role of GPER in the regulation of VEGF expression and tumor angiogenesis induced by IGF1." (PMID 29212519, 2017). "Such inhibitory effect on tumor growth is reversed by application of IGF1 ((IGF1R ligand) or MHY1485 (mTOR agonist) in vitro." (PMID 28624790, 2017). "The medical treatment with SSAs reduced the GH and IGF-1 levels effectively and decreased the tumor size to some extent." (PMID 28874187, 2017). "Insulin-like growth factor 1 (IGF1) plays a pivotal role in the progression of diverse malignancies, and has been shown to promote tumor angiogenesis by activating the HIF-1α/VEGF signaling pathway." (PMID 29212519, 2017). "In both cases the tumor was removed and histologically proved with the subsequent IGF-1 normalization and amelioration of symptoms." (PMID 28898247, 2017). "Further, in terms of extracellular acidification, there is a potential difference in the metabolism of breast epithelial cells from tumor‐affected and non‐affected breasts in response to IGF1." (PMID 28369883, 2017). "Skeletal-muscle IGF-1 was decreased in vehicle-treated tumor carriers, as compared to control value." (PMID 29152137, 2017). "A 2.3-fold and 4.6-fold increase in tumor cell viability was seen after 4 respectively 7 days in culture with 100 ng/ml of IGF-1." (PMID 28447314, 2017). "Consistently, neutralization of IGF-1 in TAB-tumor cell co-cultures led to inhibition of FGFR-3 induction and FGF-2 secretion by tumor cells." (PMID 28928360, 2017). "Related to the “FRA1‐induced” secretome IGF1 was found to be up‐regulated within tumours in response to MAPK inhibition, and this IGF1 acted on innate‐resistant cells supporting their outgrowth." (PMID 28606996, 2017). "The circulating IGF-1 level is reportedly significantly correlated with survival, the synthetic function of the liver, and tumour parameters." (PMID 29113370, 2017). "Convincing evidence has also been presented demonstrating that the IGF-1 system can stimulate tumor cell metastasis to bone." (PMID 28447314, 2017). "Together, these results illustrate that IGFBP-1 is strongly expressed in tumour tissue, while IGF-1 expression is elevated in normal tissue." (PMID 28143425, 2017). "The analysis of proton production rates in IGF1 and TNFα‐treated cells revealed differences in metabolism of normal epithelial cells from tumor‐affected versus non‐affected breasts." (PMID 28369883, 2017).